AADAC (arylacetamide deacetylase)
Description:
Displays cellular triglyceride lipase activity in liver, increases the levels of intracellular fatty acids derived from the hydrolysis of newly formed triglyceride stores and plays a role in very low-density lipoprotein assembly. Displays serine esterase activity in liver. Deacetylates a variety of arylacetamide substrates, including xenobiotic compounds and procarcinogens, converting them to the primary arylamide compounds and increasing their toxicity.
Synonyms: DAC; CES5A1
Tractability: Antibody: UniProt predicts a signal peptide or a membrane-spanning region. PROTAC: its protein half-life has been measured; a small molecule that binds it is known.
Target class: Enzyme; Hydrolase
Gene: Protein-coding gene on chromosome 3 (151,813,931 to 151,828,917, forward strand). Ensembl gene ENSG00000114771.
Subcellular location: Endoplasmic reticulum membrane; Microsome membrane
Pathways (Reactome):
Metabolism: Phase I - Functionalization of compounds
Gene Ontology:
Molecular function: acetylesterase activity; arylalkyl acylamidase activity; deacetylase activity; hydrolase activity, acting on carbon-nitrogen (but not peptide) bonds; protein binding; serine hydrolase activity; catalytic activity; diacylglycerol lipase activity; lipase activity; triacylglycerol lipase activity; carboxylic ester hydrolase activity; hydrolase activity
Biological process: detoxification; sterol metabolic process; xenobiotic metabolic process; diacylglycerol catabolic process; positive regulation of triglyceride catabolic process
Cellular component: endoplasmic reticulum membrane; membrane
Genetic constraint (gnomAD): Loss-of-function variants: 16 observed, 21.58 expected, observed/expected ratio (o/e) 0.74, 90% interval 0.5 to 1.13. The upper end of that interval is the gene's LOEUF score, 1.13, which puts it in group 4 of 6, group 1 being the genes least tolerant of losing a copy. Missense variants: 463 observed, 484.17 expected, observed/expected ratio (o/e) 0.96, 90% interval 0.88 to 1.03. Synonymous variants: 164 observed, 180.66 expected, observed/expected ratio (o/e) 0.91, 90% interval 0.8 to 1.03.
Homologues: Orthologues: chimpanzee AADAC (99% identical), macaque AADAC (93% identical), dog AADAC (75% identical), pig AADAC (75% identical), rabbit AADAC (72% identical), mouse Aadac (70% identical), rat Aadac (68% identical), guinea pig AADAC (67% identical), tropical clawed frog aadac (54% identical), zebrafish aadac (50% identical), Caenorhabditis elegans trcs-1 (28% identical), Caenorhabditis elegans T09B9.1 (27% identical), and 1 more. Paralogues in human: AADACL2 (51% identical), NCEH1 (44% identical), AADACL3 (32% identical), AADACL4 (31% identical), AFMID (15% identical).
Diseases named in the same sentence as AADAC in open-access papers:
AADAC is named in the same sentence as 16 diseases in open-access papers, as found by Europe PMC text mining. Sharing a sentence is not in itself a finding about the gene and the disease. The quoted sentences say what the papers report.
hepatoma (3 papers, 2021 to 2025). "In rat hepatoma McArdle RH-7777 cells, which also lack endogenous AADAC, expression of AADAC leads to a reduction in TG accumulation and an enhancement in fatty acid (FA) oxidation." (PMID 40376582, 2025). "Evidence that AADAC is involved in lipid metabolism has been derived from cell experiments: the expression of AADAC in rat hepatoma cells decreased intracellular triglyceride stores that was accompanied by increased fatty acid oxidation and impaired secretion of lipoproteins." (PMID 35736449, 2022). "Deficiency of AADAC, a putative triglyceride lipase, contributes to defective lipolysis of cellular triglyceride stores and very-low-density lipoprotein (VLDL) assembly in human hepatocellular carcinoma HuH7.5 cells." (PMID 34869349, 2021). "Likewise, overexpression of AADAC resulted in significantly reduced intracellular triacylglycerol levels and apolipoprotein B secretion, as well as increased fatty acid oxidation in rat hepatoma cells." (PMID 34869349, 2021).
gastric cancer (2 papers, 2022). A primary or metastatic malignant neoplasm involving the stomach. "In addition, the mRNA and protein expression levels of AADAC were high in differentiated gastric cancer (GC) cells." (PMID 35681154, 2022).
pancreatic cancer (2 papers, 2020 to 2022). "They explained their results as the protein coded by AADAC protein is extensively implicated in the hydrolysis of various drugs, whose function may be related to chemotherapy resistance in pancreatic cancer." (PMID 35446856, 2022). "The protein coded by AADAC protein is extensively implicated in the hydrolysis of various drugs, whose function may be related to chemotherapy resistance in pancreatic cancer." (PMID 32943033, 2020).
esophageal squamous cell carcinoma (1 paper, 2025). Esophageal squamous cell carcinoma (ESCC) is a type of esophageal carcinoma (EC) that can affect any part of the esophagus, but is usually located in the upper or middle third. "Hsa_circ_0043603 is a circular RNA that regulates the overexpression of AADAC by interacting with miR - 1178 - 3p, thereby inhibiting the growth and spread of esophageal squamous cell carcinoma." (PMID 40376582, 2025). "In a study by Wang investigating the regulatory effect of circular RNA hsa_circ_0043603 on the progression of esophageal squamous cell carcinoma (ESCC), it was confirmed that AADAC is a target of miR - 1178 - 3p." (PMID 40376582, 2025).
gastric adenocarcinoma (1 paper, 2022). "In conclusion, AADAC and CDKN3 genes were significantly upregulated in gastric adenocarcinoma." (PMID 35446856, 2022).
Hepatitis (1 paper, 2020). Inflammation of the liver. "Next, we examined the gene expression of two candidate genes having the extreme breakpoints identified by Trendy, namely, matrix metallopeptidase 3 (Mmp3) and arylacetamide deacetylase (Aadac) in the liver tissues of ConA-induced hepatitis model mice." (PMID 33221747, 2020).
Obesity (1 paper, 2017). Accumulation of substantial excess body fat. "We identified reduced hepatic activity of carboxylesterase 2 (CES2) and arylacetamide deacetylase (AADAC) in human obesity." (PMID 28099843, 2017).
signet ring cell carcinoma (1 paper, 2022). A usually aggressive, poorly differentiated invasive adenocarcinoma characterized by the presence of malignant glandular cells in which the nucleus is pressed to one side by the presence of intracytoplasmic mucus. "Besides, we found that the expression level of AADAC was high in the Kato III GC cell line with signet ring cell carcinoma (SRC)." (PMID 35681154, 2022).
Supraventricular tachycardia (1 paper, 2025). Supraventricular tachycardia (SVT) is an abnormally increased heart rate (over 100 beats per minute at rest) with origin above the level of the ventricles. "The research team led by Pang, while exploring the potential molecular mechanisms of supraventricular tachycardia (SVT), found that the expression of the AADAC gene was decreased in SVT samples, showing significant potential for clinical diagnosis." (PMID 40376582, 2025).
type 2 diabetes (1 paper, 2022). "In type 2 diabetes, elevated expression of AADAC in vascular smooth muscle cells altered lipid metabolism and protected patients from cardiovascular diseases." (PMID 36163032, 2022).
cancer (3 papers, 2022 to 2023). A tumor composed of atypical neoplastic, often pleomorphic cells that invade other tissues. "Apart from SOX2, other genes involved in cancer aggressiveness, such as ZIC5, FAM83A, AADAC and MYEOV, were among the top most significantly associated genes and were associated with patient outcome." (PMID 36932385, 2023). "In the future, inhibiting the expression of AADAC to control the proliferation of cancer cells will become a potential treatment strategy for GC." (PMID 35681154, 2022). "The protein-protein interaction of AADAC orthologues were related to cancer, lipid, and xenobiotic metabolism genes." (PMID 36542226, 2022).
tumor (3 papers, 2022 to 2025). "Liver- and tumor-associated markers, such as AADAC, CLRN3, GPC3, CD40, and ALB, were downregulated in LC4 cells compared to freshly isolated tumor core cells and parental tissues." (PMID 40431665, 2025). "Our study found that AADAC mainly participates in the metabolic process of tumor cells as a member of the serine lipase superfamily." (PMID 35681154, 2022).
AADAC also shares sentences with these, for which no sentence is quoted: cardiovascular diseases (1 paper); metabolic disease (1); periodontitis (1); tuberculosis (1).